ABCG1 (ATP binding cassette subfamily G member 1)
Diseases named in the same sentence as ABCG1 in open-access papers (continued):
Sharing a sentence is not in itself a finding about the gene and the disease.
infection (10 papers, 2010 to 2025). The state of being infected such as from the introduction of a foreign agent such as serum, vaccine, antigenic substance or organism. "We observed that genes involved in cholesterol uptake (Lrp2) (denoted in grey across the figures) and biosynthesis (Aacs, Hmgcs1, Mvd, Dhcr24) were significantly upregulated during infection; while those implicated in efflux (Abca1, Abcg1) showed a marked downregulation." (PMID 37871034, 2023). "In contrast, viral titers in cells treated with ABCG1-specific siRNA dropped significantly between days 2 and 5 post-infection (p < 0.001)." (PMID 41377660, 2025). "GW9662 treatment significantly promoted lipid accumulation in H37Ra-infected group and Lv-ctl group, while Lv-ABCG1 reversed the promoting effect of GW9662 on lipid accumulation in H37Ra infection group and Lv-ctl group." (PMID 35432274, 2022). "However, at 24 hours post-infection (hpi), we observed a loss of SIRT6 recruitment, indicating a potential role of SIRT6 in regulating the expression of Abca1 and Abcg1 during the early stages of infection." (PMID 37871034, 2023). "In this model, loss of the abcG1 gene did not have an observable effect on virulence, contrary to results in found in a Galleria model of infection." (PMID 30862750, 2019). "Accordingly, the least ABCG1, ABCA1 and ACAT1 proteins in BCG-infected RAW264.7 cells were found at 12 h post infection, while the least ABCA5 and ABCA6 were at 24 h post infection." (PMID 32397995, 2020). "Of interest, the least ABCA1 and ACAT1 proteins in BCG-infected bovine AMs were observed at post infection 6 h, while the ABCG1 was at 12 h, and the least ABCA5 and ABCA6 were at 24 h post infection." (PMID 32397995, 2020). "However, another Lxr target gene, Abcg1 was upregulated more than fivefold, whilst transcription of both Srbp1c and Abca1 were comparatively unaffected by infection, suggesting that there may be redundancy in the Lxr pathway involved in regulation of these genes during Plasmodium infection." (PMID 31299982, 2019). "In summary, our findings suggest that during the early stages of infection, SIRT6 deacetylates H3K9, creating a platform for G9a-mediated demethylation of H3K9, ultimately leading to the transcriptional inactivation of Abca1 and Abcg1." (PMID 37871034, 2023).
metabolic disease (7 papers, 2017 to 2024). A congenital disorder (due to inherited enzyme abnormality) or acquired (due to failure of a metabolically important organ) disorder resulting from an abnormal metabolic process. "Although no genetic disease caused by ABCG1 mutations has been reported, decrease in ABCG1 expression levels was observed in metabolic disorders." (PMID 35004908, 2021). "Among ABC transporters, ABCA1 and ABCG1 have received the most attention regarding metabolic diseases." (PMID 32774439, 2020). "Recently, the role of ABCA1 and ABCG1 in metabolic diseases has been the most studied." (PMID 32774439, 2020).
inflammation (4 papers, 2021 to 2025). Aberrant reaction of the microcirculation characterized by movement of fluid and leukocytes from the blood into extravascular tissues. "A study on murine models revealed a connection between the deficiency of ABCG1 in alveolar macrophage and pulmonary granulomatous inflammation." (PMID 40149530, 2025). "Given that continual apoptosis causes persistent severe lung inflammation, we hypothesized that ABCG1 deficiency would increase MWCNT-induced apoptosis thereby promoting granulomatous inflammation and fibrosis." (PMID 35008476, 2021). "In conclusion, the current study proposes a potential role of ABCG1 in fibrosis secondary to a chronic pulmonary granulomatous inflammation induced by MWCNT." (PMID 35008476, 2021). "Given that persistent apoptosis aggravates lung inflammation and efferocytosis increases TGF-β production, our observations suggest that MWCNT may increase both apoptosis and efferocytosis events in BAL cells of ABCG1 KO mice, resulting in enhanced chronic granulomatous inflammation and fibrosis." (PMID 35008476, 2021).
neurodegenerative disease (2 papers, 2018 to 2025). A disorder of the central nervous system characterized by gradual and progressive loss of neural tissue and neurologic function. "Targeting ABCG1 improves cholesterol efflux in neurodegenerative diseases and reduces chemoresistance in ES-CSCs and OST-CSCs." (PMID 40370434, 2025). "We also noted that other genes like MT-CO2, MT2A, and ABCG1 are placed in specific nodes of our molecular networks, thus suggesting that they may play important role/s in ALS, as it has been already reported in other neurodegenerative diseases like AD." (PMID 30210287, 2018).
bacterial infection (1 paper, 2021). "To investigate how bacterial infection impacts placental efflux transport potential, we investigated the expression of the of Abca1, Abcb1a, Abcb1b, Abcb4, Abcc2, Abcc5, Abcf2, Abcg1 and Abcg2 mRNAs in the mouse placenta at GD15.5 or GD18.5 following LPS challenge (4 h)." (PMID 34394055, 2021).
hematological diseases (1 paper, 2020). "Interestingly, upon MAT2A inhibition, we detected the cholesterol efflux transporters ABCG1 and ABCA1 of the cholesterol metabolism to be significantly upregulated, resulting in known anti-proliferative and apoptotic effects in hematological diseases." (PMID 32456310, 2020).
lung (1 paper, 2024). "Similar features are in part observed in knockout animals for some key LXR target genes, such as Abca1 -/- or Abcg1-/-, including the development of lung lipidosis, supporting that LXR activity is key to modulate lipid metabolism in the lung." (PMID 38970705, 2024).
ABCG1 also shares sentences with these, for which no sentence is quoted: Dyslipidaemia (2 papers); endothelial dysfunction (2); leukocytosis (2); acute lymphoblastic leukemia (1); acute myeloid leukemia (1); age-related macular degeneration (1); aortic atherosclerosis (1); arteriopathy (1); autoimmune PAP (1); bladder tumor (1); bone cancer (1); brain tumor (1); cardiac hypertrophy (1); cholesterol metabolism disorders (1); chronic kidney disease (1); chronic obstructive pulmonary disease (1); COVID-19 (1); diabetic neuropathy (1); emphysema (1); gout (1); heart disease (1); infarction (1); injury (1); insulinoma (1); ischemic cardiomyopathy (1); leukemia (1); Listeria monocytogenes infection (1); liver cancer (1); liver diseases (1); malignant glioma (1).
A further 13 diseases each share a sentence with ABCG1 in 1 paper.